ANK3 (ankyrin 3)
Description:
Membrane-cytoskeleton linker. May participate in the maintenance/targeting of ion channels and cell adhesion molecules at the nodes of Ranvier and axonal initial segments. In skeletal muscle, required for costamere localization of DMD and betaDAG1 (By similarity). Regulates KCNA1 channel activity in function of dietary Mg(2+) levels, and thereby contributes to the regulation of renal Mg(2+) reabsorption. Required for intracellular adhesion and junctional conductance in myocytes, potentially via stabilization of GJA1/CX43 protein abundance and promotion of PKP2, GJA1/CX43, and SCN5A/Nav1.5 localization to cell-cell junctions (By similarity). [Isoform 5]: May be part of a Golgi-specific membrane cytoskeleton in association with beta-spectrin.
Synonyms: ANKYRIN-G; MRT37
Tractability: Antibody: UniProt places it where antibodies can reach, with high confidence; its Gene Ontology location is reachable by antibodies, with high confidence; the Human Protein Atlas places it where antibodies can reach. PROTAC: ubiquitination databases record sites on it; its protein half-life has been measured.
Gene: Protein-coding gene on chromosome 10 (60,026,298 to 60,733,490, reverse strand). Ensembl gene ENSG00000151150.
Subcellular location: Cytoplasm, cytoskeleton; Cell projection, axon; Cell membrane, sarcolemma; Postsynaptic cell membrane; Lysosome; Cell membrane, sarcolemma, T-tubule; Cytoplasm, cytoskeleton (Isoform 5); Golgi apparatus
Subcellular location (Human Protein Atlas): Plasma membrane
Pathways (Reactome):
Cell-Cell communication: Regulation of CDH1 posttranslational processing and trafficking to plasma membrane
Developmental Biology: Interaction between L1 and Ankyrins
Vesicle-mediated transport: COPI-mediated anterograde transport
Gene Ontology:
Molecular function: protein binding; protein transporter activity; structural constituent of cytoskeleton; cadherin binding; channel activator activity; cytoskeletal anchor activity; cytoskeletal protein binding; protein-macromolecule adaptor activity; sodium channel regulator activity; spectrin binding; transmembrane transporter binding
Biological process: establishment of protein localization; Golgi to plasma membrane protein transport; maintenance of protein location in plasma membrane; membrane assembly; mitotic cytokinesis; plasma membrane organization; protein localization to plasma membrane; axonogenesis; cellular response to magnesium ion; magnesium ion homeostasis; negative regulation of delayed rectifier potassium channel activity; neuromuscular junction development; neuronal action potential; photoreceptor cell maintenance; positive regulation of cell communication by electrical coupling; positive regulation of gene expression; positive regulation of homotypic cell-cell adhesion; positive regulation of membrane depolarization during cardiac muscle cell action potential; positive regulation of membrane potential; positive regulation of protein targeting to membrane; positive regulation of sodium ion transport; protein localization to axon; regulation of potassium ion transport; cytoskeleton organization; Golgi vesicle transport; and 1 more
Cellular component: axon initial segment; basal plasma membrane; basolateral plasma membrane; bicellular tight junction; lateral plasma membrane; photoreceptor outer segment membrane; plasma membrane; sarcolemma; cell surface; costamere; cytosol; dendrite; endoplasmic reticulum; Golgi apparatus; intercalated disc; lysosome; neuromuscular junction; neuron projection; node of Ranvier; postsynaptic membrane; rod photoreceptor outer segment; sarcoplasmic reticulum; spectrin-associated cytoskeleton; T-tubule; Z disc; and 3 more
Genetic constraint (gnomAD): Loss-of-function variants: 43 observed, 345.8 expected, observed/expected ratio (o/e) 0.12, 90% interval 0.096 to 0.16. The upper end of that interval is the gene's LOEUF score, 0.16, which puts it in group 1 of 6, group 1 being the genes least tolerant of losing a copy. Missense variants: 4,283 observed, 5,359.9 expected, observed/expected ratio (o/e) 0.8, 90% interval 0.78 to 0.82. Synonymous variants: 1,860 observed, 1,983.1 expected, observed/expected ratio (o/e) 0.94, 90% interval 0.9 to 0.98.
Gene-disease validity (ClinGen):
ClinGen rates the evidence that ANK3 causes each of these diseases.
intellectual disability (autosomal recessive): Moderate.
Homologues: Orthologues: chimpanzee ANK3 (99% identical), macaque ANK3 (99% identical), dog ANK3 (95% identical), pig ANK3 (93% identical), rabbit ANK3 (91% identical), rat Ank3 (87% identical), tropical clawed frog ank3 (71% identical), zebrafish ank3a (57% identical), mouse Ank3 (38% identical), zebrafish ank3b (11% identical). Paralogues in human: ANK2 (37% identical), ANK1 (22% identical), ASB7 (2% identical).
Diseases named in the same sentence as ANK3 in open-access papers:
ANK3 is named in the same sentence as 106 diseases in open-access papers, as found by Europe PMC text mining. Sharing a sentence is not in itself a finding about the gene and the disease. The quoted sentences say what the papers report.
bipolar disorder (61 papers, 2011 to 2025). A disorder of the brain that causes unusual shifts in mood, energy, activity levels and the ability to carry out day-to-day tasks. "At the gene level, both STAB1 and ANK3 have been associated with bipolar disorder and schizophrenia." (PMID 41211100, 2025). "Pathogenic variants in ANK3 are associated with various neurological disorders, including bipolar disorder, schizophrenia, and autism spectrum disorder." (PMID 38702695, 2024). "Different studies have highlighted the role of ANK3 gene single nucleotide polymorphims (SNPs) as a risk factor for bipolar disorder." (PMID 37190119, 2023). "ANK3 mRNA levels moderated the association between childhood sexual abuse and age at onset of mania/hypomania (ßsexual abuse × ANK3 = − 1.23, p = 0.006, CI = − 2.10 to − 0.36; r2 = 0.02)." (PMID 37620394, 2023). "Genome-wide association studies (GWAS) have linked Ank3 with psychiatric disorders, including bipolar disorder." (PMID 37344232, 2023). "For example, ANK3 encodes ankyrin-G and is linked to autism spectrum disorders, attention deficit hyperactivity disorder, intellectual disability, and bipolar disorder." (PMID 35089962, 2022). "Recent evidence has implicated the ANK3 gene, encoding ankyrin-G, in bipolar disorder (BD), schizophrenia (SZ), and autism spectrum disorder (ASD)." (PMID 35794211, 2022). "The gene ankyrin-3 (ANK3) has been consistently associated with bipolar disorder (BD) in several genome-wide association studies (GWAS)." (PMID 35091539, 2022). "ANK3 is a scaffolding protein and genetic variants annotated to this gene are associated with various psychiatric disorders including schizophrenia, bipolar disorder, and autism." (PMID 33371772, 2021). "The intronic single nucleotide polymorphism (SNP) rs10994336 within the ANK3 has emerged as one of the most replicated risk variants for bipolar disorder (BD) in genome-wide association studies." (PMID 34421516, 2021). "Genome-wide association studies have shown that ANK3 plays a role in schizophrenia and bipolar disorder." (PMID 34248821, 2021). "Ankyrin-3 (ANK3), encoding the adaptor protein Ankyrin-G (AnkG), has been indicated as an important factor in the pathophysiology of schizophrenia and bipolar disorder." (PMID 33718116, 2020). "Seven genes were implicated in both positive psychotic experiences in UK Biobank and schizophrenia: ANK3, a gene in the 10q21.2 region, has previously been associated with bipolar disorder and schizophrenia." (PMID 32152294, 2020). "ANK3 has been associated with several psychiatric disorders, including schizophrenia, bipolar disorder, and autism spectrum disorder." (PMID 31866821, 2019). "Together, these results point to the likely molecular mechanism underlying ANK3 ́s association with bipolar disorder." (PMID 30297702, 2018). "Ankyrin-3 (ANK3) is one of the few genes that have been consistently identified as associated with bipolar disorder by multiple genome-wide association studies." (PMID 30297702, 2018). "Consistent with this idea, genome-wide association studies have identified ANK3 as one of the most significant risk loci for bipolar disorder, and to a lesser degree schizophrenia." (PMID 28536506, 2017). "ANK3 has been associated with autism susceptibility, as well as with increased risk for and modulation of working memory deficits in bipolar disorder and schizophrenia." (PMID 28118382, 2017). "It is worthwhile to mention that ANK3 has been shown to be associated with bipolar disorder and schizophrenia." (PMID 27449795, 2016). "For example, the ankyrin-G protein encoded by Ank3 organizes synaptic microtubules and is involved in protein trafficking, neurogenesis and neuroprotection, and in the aetiology of bipolar disorder and schizophrenia." (PMID 26694817, 2015).
bipolar disorder (continued). "Genome-wide association studies have found ANK3 (the gene encoding ankyrin G) to be a susceptibility gene for schizophrenia, and associated identified single nucleotide polymorphisms (SNPs) with bipolar disorder." (PMID 24913350, 2014). "Ankyrin-G has been identified in GWAS as a potential risk gene for bipolar disorder with significantly associated SNPs in ANK3 as well as other bipolar disorder candidate genes, including one that maps to a non-conservative amino acid change." (PMID 25191280, 2014). "Genome-wide association studies (GWAS) have implicated ANK3 as a susceptibility gene for bipolar disorder (BP)." (PMID 23730306, 2013). "In schizophrenia, both CACNA1C and ANK3 were identified, and in bipolar disorder TRANK1 and CACNB2 were also significantly associated." (PMID 23637625, 2013). "Several genome-wide association studies for bipolar disorder (BD) have found a strong association of the ANK3 gene." (PMID 23597238, 2013). "A GWA study based on pooled DNA found association with bipolar disorder and rs9804190 located intronic between exon 36 and 37 at the locus ANK3." (PMID 21702894, 2011). "Genome wide association studies reported two single nucleotide polymorphisms in ANK3 (rs9804190 and rs10994336) as independent genetic risk factors for bipolar disorder." (PMID 21702894, 2011). "Within the debate on common susceptibility genes for schizophrenia and bipolar disorder, we tried to investigate common findings by analyzing association of ANK3 with schizophrenia, bipolar disorder and unipolar depression." (PMID 21702894, 2011). "Similarly, the 5′bipolar disorder risk allele overlaps two first exons of Ank3 (exon1b and exon1e) and their associated promoters." (PMID 39804991, 2025). "Large-scale GWAS have identified Syne1 as a top risk locus for major psychiatric disorders including schizophrenia, bipolar disorder, major depression, ADHD, and autism spectrum disorder, with particularly strong associations with bipolar disorder, second only to ANK3." (PMID 39304885, 2024). "In addition, genetic variants in ANK3 have been associated with bipolar disorder, schizophrenia, and ASD." (PMID 36604605, 2023). "Mutations and SNPs (single nucleotide polymorphims) in the ANK3 gene that code for ankyrinG are related to bipolar disorder, schizophrenia, post-traumatic stress disorder (PTSD), attention-deficit hyperactivity disorder (ADHD), autism spectrum disorders, or intellectual disability (ID)." (PMID 37190119, 2023). "Several recent studies have reported that ANK3 is strongly associated with bipolar disorder." (PMID 35646694, 2022). "Moreover, GSK3β inhibits neuronal transport by phosphorylating the kinesin light/heavy chains in an ANK3 deficiency model of bipolar disorder." (PMID 36504683, 2022). "For example, a common genetic variant implicating the ANK3 gene has consistently been associated with risk for bipolar disorder, and transgenic mice deficient for the related ANK3 exon 1b have a gene dosage-dependent phenotype with behavioral changes and epilepsy." (PMID 33287748, 2020). "Our study cannot confirm ANK3 as a common risk factor for both diseases, challenging the hypothesis that bipolar disorder and schizophrenia are just different phenotypes of the same disease." (PMID 21702894, 2011). "In present study, therefore, we selected 13 ANK3 SNPs whose association with schizophrenia or bipolar disorder has been previously investigated and evaluated whether these polymorphisms are associated with schizophrenia risk in a northern Chinese Han population." (PMID 27811378, 2016). "Both ANK3 and ZNF804A are candidate genes associated with schizophrenia and bipolar disorder based on genome-wide association studies." (PMID 38702695, 2024). "Patients with high ANK3 mRNA levels and severe scores of sexual traumas had the earliest age at onset of mania/hypomania (ß = − 0.64; P = 0.01, CI = − 1.14 to − 0.15)." (PMID 37620394, 2023).
bipolar disorder (continued). "ANK3 is a leading bipolar disorder (BD) candidate gene in humans and provides a unique opportunity for studying epilepsy-BD comorbidity." (PMID 38123552, 2023). "Patients with higher ANK3 mRNA also showed a trend of more manic/hypomanic episodes and earlier age at onset of mania/hypomania." (PMID 37620394, 2023). "A rare loss-of-function splice-site SNP (rs41283526*G) in a minor isoform of ANK3 (incorporating exon ENSE00001786716) was recently identified as protective of bipolar disorder and schizophrenia." (PMID 30297702, 2018). "In accordance with this, DISC1, ANK3 and ASPM, whose mutations are associated with schizophrenia, bipolar disorder and autism spectrum disorder, have been shown to regulate Wnt/β-catenin signaling activity during cortical neurogenesis." (PMID 28103279, 2017). "These include ANK3, SORL1 and a region of chromosome 6p containing several genes implicated in schizophrenia and bipolar disorder." (PMID 25897833, 2015). "The importance of ANK3 to serious mental illness is further supported by recent GWAS implicating ANK3 in schizophrenia and bipolar disorder." (PMID 24478629, 2014). "Genetic markers in the genes encoding ankyrin 3 (ANK3) and the α-calcium channel subunit (CACNA1C) are associated with bipolar disorder (BP)." (PMID 24716743, 2014). "Nevertheless, the whole-genome sequencing identified a number of rare and putative damaging variants in ANK3, ODZ2, ODZ4 and ITIH3 genes, located within or surrounding significant genome-wide association hits for bipolar disorder." (PMID 24625924, 2014). "Previous GWA studies of bipolar disorder have implicated several potential susceptibility genes, such as SYNE1 on chromosome 6q25.2, ODZ4 on 11q14.1, ANK3 on 10q21.2, CACNA1C on 12p13.3, and NCAN on 19p13.1." (PMID 23326512, 2013). "While ANK3 has previously been implicated in bipolar disorder and schizophrenia, secondary CNV analysis of FOXP1 and ANK3 in 19,566 patients with ASD revealed a significant CNV burden for FOXP1, but not ANK3." (PMID 22736078, 2012). "Of note, the gene ankyrin 3, node of Ranvier (ankyrin G), or ANK3, has been reported in previous GWA studies to be associated with schizophrenia and bipolar disorder." (PMID 21390307, 2011). "Here we characterize a deeply conserved microexon E35a in Ank3 encoding ankyrin-G (AnkG), a multifaceted adaptor protein best known as a master organizer of the axon initial segment (AIS) and as a leading genetic risk factor for bipolar disorder." (PMID 41427402, 2025). "Moreover, ANK3 mRNA can be regulated by the expression level of microRNAs in bipolar disorder patients, such as miR34a and miR10b-5p." (PMID 37190119, 2023). "Furthermore, some interactions between SNPs in association with bipolar disorder were described in a discovery GWAS dataset, of which the most significant ones were SNPs from KCNQ2 with SNPs from ANK3." (PMID 32120974, 2020). "Moreover, a different study found an epistatic interaction between ANK3 and KCNQ2 SNPs in bipolar disorder, i.e. the effect of a mutation in one gene was dependent on the mutation present in the other gene." (PMID 24913350, 2014). "The ANK3 locus was not indicated in the conjunctional analysis, which indicates that the overlap is mostly driven by the association in bipolar disorder." (PMID 23637625, 2013). "Both Meta-analyses suggested a specific effect of ANK3 for bipolar disorder." (PMID 21702894, 2011). "Furthermore, ANK3 has been found to be associated with schizophrenia and bipolar disorder; however, to our knowledge, it has not been well studied in epilepsy yet." (PMID 21390307, 2011). "Analysis of previous associated SNPs in different LD-Blocks, located intronic (rs9804190 and rs10761482) or 30 kb downstream of ANK3 (rs10994336) found a nominally significant association of SNP rs10761482 with bipolar disorder (p = 0.015, OR 1.304) but not with schizophrenia." (PMID 21702894, 2011).
bipolar disorder (continued). "Of interest, the ITIH3 region (3p21.1), ANK3 (10q21) and CACNA1C (12p13.3) were discovered previously in the same, combined schizophrenia and bipolar disorder sample." (PMID 23637625, 2013). "For bipolar disorder the most promising results have been reported for CACNA1C and ANK3 (ankyrin 3, node of Ranvier)." (PMID 21702894, 2011). "Furthermore, variants of genes like SLC6A4 and ANK3 have also been associated with a higher risk of depression or bipolar disorder when present in two copies, but not when present in only one copy, suggesting that heterozygosity for such variants may confer protection against depression." (PMID 37124257, 2023). "All these genes are associated with psychiatric conditions, ranging from ID i.e., CNKSR2, CTNNB1, ANK3, CASK and ASD i.e., CTNND2, ANK3 to schizophrenia i.e., CNKSR2 (GWAS, PGC-SCZ 2014) and bipolar disorder ANK3." (PMID 28713243, 2017). "Of interest, the VRK2 region (2p16.1) was identified in the previous sample after including a large schizophrenia replication sample, and the ITIH4 region (3p21.1), ANK3 (10q21) and CACNA1C (12p13.3) were discovered previously in the same, combined schizophrenia and bipolar disorder sample." (PMID 23637625, 2013). "This may not be that surprising since bipolar disorder associated risk genes such as SHANK2 and ANK3 are shared between these disorders." (PMID 36504683, 2022).